ASS1 (argininosuccinate synthase 1)
Diseases named in the same sentence as ASS1 in open-access papers (continued):
Sharing a sentence is not in itself a finding about the gene and the disease.
movement disorder (1 paper, 2019). Neurological conditions resulting in abnormal voluntary or involuntary movement, which may impact the speed, fluency, quality and ease of movement. "Indeed, residual enzymatic ASS1 activity is associated with the presence of movement disorder and hepatocellular injury." (PMID 31469252, 2019). "The observation, that clinical manifestations are not present in all individuals below the defined thresholds of residual enzymatic ASS1 activity can also be corroborated for further outcome variables, such as movement disorder, and hepatocellular injury." (PMID 31469252, 2019). "Affected individuals with a residual enzymatic ASS1 activity below or equal to 19.3% suffer more often from movement disorders (n = 60, P = 0.03, recursive partitioning)." (PMID 31469252, 2019).
ASS1 also shares sentences with these, for which no sentence is quoted: citrullinemia (16 papers); inherited diseases (4); leiomyosarcoma (4); ornithine transcarbamylase deficiency (4); acute lymphoblastic leukemia (2); alveolar soft part sarcoma (2); cystinuria (2); diabetic kidney disease (2); Epithelioid Mesothelioma (2); esophageal squamous cell carcinoma (2); GI tumors (2); hepatocellular adenoma (2); leishmaniasis (2); preeclampsia (2); acute promyelocytic leukemia (1); adenocarcinoma (1); Adrenocortical carcinoma (1); amyloid (1); angiosarcoma (1); Anxiety (1); arginase deficiency (1); argininosuccinic aciduria (1); Arthritis (1); autism (1); autoimmune myocarditis (1); bacterial infections (1); biotinidase deficiency (1); Bladder urothelial carcinoma (1); blastoma (1); bone tumors (1).
A further 62 diseases each share a sentence with ASS1 in 1 paper.